IL10 (interleukin 10)
Diseases named in the same sentence as IL10 in open-access papers (continued):
Sharing a sentence is not in itself a finding about the gene and the disease.
pancreatic cancer (continued). "Furthermore, a study on pancreatic cancer reported that a close proximity of immunosuppressive IL10+ myelomonocytes to cytotoxic granzyme-B+ CD8+ T-cells instead of PD-1+ CD4 + T-cells was associated with shorter survival in non-neoadjuvant treated patients." (PMID 38386105, 2024). "There is also evidence for the ability of NLRP3 signaling to contribute to the establishment of an immunosuppressive microenvironment in pancreatic cancer by promoting T cells to undergo tolerogenic differentiation and through the IL-10-mediated suppression of adaptive immunity." (PMID 37885032, 2023). "Their functions are active, and they secrete large amounts of interleukin-10 (IL-10), TGF-β, IDO and other immunosuppressive factors to form an immunosuppressive TME in pancreatic cancer, which inhibits the immune response and causes immune escape to alter the effect of immunotherapy." (PMID 37741887, 2023). "IL-10 modified hMSCs could inhibit the growth of pancreatic cancer, and IL-15 produced by MSCs could also significantly inhibit the growth of pancreatic cancer." (PMID 35281017, 2022). "Feng and co-authors analyzed the serum IL-10 levels in patients with pancreatic cancer." (PMID 36009467, 2022). "Finally, we demonstrated that PF inhibits IL-6 and IL-10 expression and p38 phosphorylation in pancreatic cancer cells, thereby reducing inflammation." (PMID 36339551, 2022). "Additionally, in pancreatic cancer, cells harboring KRASG12D mutations secrete high levels of the anti-inflammatory mediators TGF-β and IL10, crucial chemokines for sustaining an immunosuppressive environment and cancer cell immune escape." (PMID 35159208, 2022). "Similarly, in pancreatic cancer, it was also confirmed that IL-10 stimulates the conversion of CD4+ T cells to CD4+ FoxP3+ Tregs cells." (PMID 35159208, 2022). "IL10-modified hMSCs could also inhibit the growth of pancreatic cancer by inhibiting the secretion of pro-inflammatory cytokines IL6 and TNF-α and tumor angiogenesis." (PMID 35281017, 2022). "The TME in pancreatic cancer is composed of various types of cells that secrete abundant cytokines, including tumor cells, immunosuppressive cells, CAFs, inhibitory cytokines such as IL-6, IL-10 and TGF-β." (PMID 34290984, 2021). "The results indicated that TNFSF9 may promote pancreatic cancer cells to release IL-10 and TGF-β through Wnt signal to promote M2 polarization of macrophages." (PMID 34517345, 2021). "In a mouse model of pancreatic cancer, HPSE overexpression was associated with increased macrophage expression of M2 cytokines IL-6, IL-10, CCL-2, VEGF, and macrophage scavenger receptor-2 (MSR-2), increased tumor size, and increased levels of tumor-infiltrating macrophages." (PMID 34461608, 2021). "Foxp3 and CTLA-4 mRNA expression are higher in Tregs from the peripheral blood of patients with progressed and advanced pancreatic cancer, and there should further be a positive correlation between the IL-10 or TGFβ levels and the progression of pancreatic cancer." (PMID 30060755, 2018). "IL-6 promotes the expansion of HCC stem cells, and IL-10 promotes EMT in pancreatic cancer cells." (PMID 29338742, 2018). "Studies demonstrated that M2-polarized TAMs promoted EMT in pancreatic cancer cells, suggesting a novel mechanism by which M2-polarized TAMs may contribute to the aggressive behavior of pancreatic cancer cells by TLR4/IL-10 signaling." (PMID 28970834, 2017). "Among the incriminated actors, some (IFNG, IL10, MDSC...) are directly implicated in and might explain the upregulation of PDL1 in pancreatic cancer." (PMID 27589570, 2016). "As we can see, plasma IL-10 concentrations was significantly increased in pancreatic cancer patients (median = 2.45 pg/mL, n = 34), with comparison to both benign pancreatic disease patients (median = 1.99 pg/mL, n = 15, P = 0.047), and normal donors (median = 1.10 pg/mL, n = 13, p<0.001)." (PMID 24520352, 2014).
pancreatic cancer (continued). "Thus, our study has further demonstrated that circulating IL-10 levels were significantly increased in pancreatic cancer patients compared to patients with benign pancreatic diseases." (PMID 24520352, 2014). "Univariate Cox model analysis further demonstrated that PS, clinical stage, CRP levels, and CEC levels are all associated with the survival of pancreatic carcinoma patients, while multivariate Cox analysis showed that CEC and IL-10 levels are strongly associated with survival." (PMID 22731825, 2012). "Finally, an immunosuppressive tumor microenvironment induced by pancreatic cancers suppresses CD8+ CTL function through secretion of IL-10 and TGF-β from Treg cells." (PMID 21922022, 2011). "In the pancreatic cancer microenvironment, various factors, such as CSF-1, IL-4, IL-13, TGFβ and IL-10, promote myeloid progenitor cell differentiation into monocytes and macrophages, which in turn secrete immunosuppressive cytokines, chemokines and enzymes, such as TGFβ, IL-10, CCL17, and CCL22." (PMID 39195299, 2024). "Additionally, our colleagues discovered that IgA+ B cells, which expressed PD-L1, IL-10 and Fas-L, could suppress anti-tumor immunity in oxaliplatin-treated pancreatic cancer, one of the mechanisms responsible for chemotherapy tolerance." (PMID 38720319, 2024). "Therefore, we speculated that TLR4 inhibition by L. casei & L. reuteri in pancreatic cancer cells led to a decrease in IL-10 secretion, which in turn drove M1 macrophage polarization in TME." (PMID 37904102, 2023). "Manipulating IL-10 pathways may provide therapeutic benefits for pancreatic cancer patients." (PMID 35493517, 2022). "Small interfering RNA (siRNA)-mediated knockdown of TLR4 or inhibition of TLR4/IL-10 signaling with neutralizing antibodies could reverse the EMT of the pancreatic cancer cells, suggesting that M2-polarized TAMs can promote EMT and aggressive behavior in pancreatic cancer cells." (PMID 35501802, 2022). "IL-10 contributes to the formation of an immunosuppressive tumor microenvironment (TME) in cancers such as gastric, ovarian, bladder, and pancreatic cancers and is correlated with poor patient outcomes." (PMID 41051603, 2025). "In the pancreatic cancer TME, sialic acid modulates monocytes to secrete IL-10 and IL-6, which subsequently activate the SIGLEC9 receptor, promoting the polarization and differentiation of monocytes into immunosuppressive TAMs." (PMID 41418390, 2025). "In pancreatic cancer cells, M2-polarized TAMs promote EMT through TLR4/IL-10 signaling, which in turn enhances proliferation, migration and the proteolytic activity of MMP2 and MMP9." (PMID 39195299, 2024). "In our previous study, we observed that a combination of CXCL1, IL10, and CCL4 significantly impacted pancreatic cancer cells." (PMID 39518934, 2024). "Thus, IL-10 might be a potential biomarker for predicting pancreatic cancer prognosis." (PMID 39195299, 2024). "M2-polarized tumour-associated macrophages, which secrete cytokine factors such as IL-10 and TGF-β to support immunosuppression in tumours, have been linearly correlated with IgG4+ plasma cells in pancreatic cancer." (PMID 34986892, 2022). "PF inhibits the proliferation of pancreatic cancer cells by interfering with the MAKP signaling pathway, IL-10, IL-6, and additional inflammatory factors." (PMID 36339551, 2022). "However, high levels of IL-6, IL-10, and IL-8 in serum have been reported to negatively correlate with survival in pancreatic cancer patients, due to their role in stimulating inflammation and adverse changes in the tumor microenvironment that spurs the growth and development of pancreatic tumors." (PMID 34136405, 2021). "In summary, TNFSF9 promotes the release of IL-10 and TGF-β from pancreatic cancer cells by activating Wnt signaling, thereby promoting M2 polarization of macrophages." (PMID 34517345, 2021).
pancreatic cancer (continued). "To assess the role of MSCs modified by IL10 on mice with tumors in vivo, we established a subcutaneous mice model with pancreatic cancer, MSC-IL10 was injected into the tail vein once and the effect on tumor growth on mice was evaluated." (PMID 32742480, 2020). "High levels of cytokines IL-1β, IL-6, IL-8, IL-10, TGF-β, and TNF-α are observed in patients with pancreatic cancer compared to healthy patients." (PMID 32174830, 2020). "On the contrary, when IL-10 is secreted by M2-like TAMs in co-culture with pancreatic cancer cells, it promotes epithelial–mesenchymal transition of cancer cells via toll like receptor 4 (TLR4)/IL-10 signaling." (PMID 32326073, 2020). "In particular, the KRASG12D mutation and MEK/ERK pathway activation was shown to up-regulate production of IL-10 and TGF-β, thus promoting CD4 T cells conversion in Tregs in pancreatic cancer." (PMID 31665076, 2019). "For example, TGFβ, IL-10 and VEGF, which are considered to be immunosuppressive cytokines secreted by pancreatic cancer cells, Tregs, and TAMs, can promote desmoplasia, angiogenesis/lymphangiogenesis, EMT, and formation of the pre-metastatic niche." (PMID 30060755, 2018). "IL-6 and IL-10 were significantly increased in both the HCC and GBC groups, IL-2, IL-6, IL-10, and TNF-α in the cholangiocellular carcinoma group, and IL-2, IL-6, IL-8, and TNF-α in the pancreatic cancer group." (PMID 29410961, 2017). "Apart from inflammation, the suppression of the lymphocyte-mediated immune response by inhibitory mediators such as IL-10 and TGF-β also plays a crucial role in the progression of pancreatic carcinomas." (PMID 29383181, 2017). "FOXP3, the master transcription factor for regulatory T-cells (Tregs), and its effective cytokine IL10, were also upregulated in the “PDL1-up” group of pancreatic cancers." (PMID 27589570, 2016). "Several cytokines, such as interleukin-10 (IL-10), macrophage migration inhibitory factor (MIF), and CCL-18, have been shown to induce EMT in pancreatic cancer cells." (PMID 27191744, 2016). "Application of TLR4 siRNA and neutralizing antibodies against TLR4 and IL-10 expressed on M2-polarized TAM markedly inhibited E-cadherin reduction and the upregulation of Snail and vimentin in pancreatic cancer cells." (PMID 27191744, 2016). "M2 can promote epithelial-mesenchymal transition in pancreatic cancer cells, partially through TLR4/IL-10 signaling pathway." (PMID 26879926, 2016). "After peptide stimulation in the presence of anti-IL10 blockade, the frequency of MSLN-specific CD8+ T cells was increased in PBMC of 2 out of 7 patients with pancreatic cancer.." (PMID 24520352, 2014). "DC pulsed with pancreatic cancer cell lysates induced secretion of Th1 cytokine IFN-γ, IL-2 and the Th2 cytokine IL-10." (PMID 25521461, 2014). "We were able to show that the serum of exercise-trained patients with advanced-stage pancreatic cancer (PC) leads to the release of certain myokines, such as C-X-C motif ligand 1 (CXCL1), Interleukin 10 (IL10), and C-C motif chemokine ligand 4 (CCL4), from contracting skeletal muscle." (PMID 39518934, 2024). "Compounding this challenge, the pancreatic tumor cells themselves produce and release potent immunosuppressive agents, such as Transforming Growth Factor-beta (TGF-β), Interleukin-10 (IL-10), Interleukin-6 (IL-6), Vascular Endothelial Growth Factor (VEGF), and the Fas ligand." (PMID 37958483, 2023). "In this study, we evaluated the release of cytokines in the supernatant of VPA-treated pancreatic cancer cells and found that VPA increased the release of IL-8 and to a lesser extent than IL-10, while the production of VEGF was reduced compared to that in untreated cancer cells." (PMID 37603071, 2023). "Moreover, SLC40A1 expression positively correlates with the expression of TAM genes (CD68, MRC1, IL10, CSF1, and CSF1R) in pancreatic tumors." (PMID 36333531, 2022).
pancreatic cancer (continued). "Additionally, IL-10 and TGF-β released by pancreatic cancer cells are described to suppress cytotoxic CD8+ T cell-mediated tumor killing." (PMID 35159208, 2022). "In pancreatic cancer, evidence exists for changes toward a typical pro-inflammatory cytokine expression: in tissues higher MIF, IL-8, and CXCR-4 expression and reduced HLA-DR expression, and in serum higher IL-6 and IL-10 levels." (PMID 35034144, 2022). "In addition, TNFSF9 also regulates the release of cytokines IL-10 and transforming growth factor-β (TGF-β) in pancreatic cancer cells through Wnt signaling to induce the M2 polarization of macrophages and promote the migration of PC cells." (PMID 34517345, 2021). "Furthermore, our study found that co-culture with DKK3-overexpressing pancreatic cancer cells upregulated IFN-γ, IL-2, and IL-17, inhibited tIL-4 and IL-10 in activated CD4+ T cells." (PMID 34391478, 2021). "In addition, there are various soluble immunosuppressive molecules (such as TGF-β, IL-10, IL-23, IDO and VEGF-A, etc.)and immunosuppressive cells (Tregs, MDSCs and TAMs) in the tumor microenvironment of pancreatic cancer." (PMID 35155218, 2021). "In this article, we further found that the M2 polarization of macrophages co-cultured with TNFSF9 knockdown pancreatic cancer cells was reduced, and this result was dependent on the activation of Wnt signaling by TNFSF9 to promote the release of IL-10 and TGF -β in pancreatic cancer cells." (PMID 34517345, 2021). "This study combined pegylated IL-10 with FOLFOX in previously treated metastatic pancreatic cancer patients and, unfortunately, that did not result in improvement in survival outcomes, leading to further disappointment." (PMID 35582227, 2020). "Furthermore, the mechanism of in vivo growth inhibition of pancreatic cancer cells by MSC modified by IL10 was studied using immunohistochemistry and alginate assays, which confirmed that MSC-IL10 inhibited the formation of angiogenesis in tumors." (PMID 32742480, 2020). "For example, M2-like TAMs can increase MMP2 and MMP9 activity in pancreatic cancer cells and decrease E-cadherin, indicating that EMT and Toll-like receptor (TLR) 4 expression and IL-10 production, are upregulated in M2-like TAMs to stimulate EMT when cocultured with pancreatic cancer cells." (PMID 30060755, 2018). "They discovered that suppressing interleukin-10, an immune inhibitory cytokine secreted by Tregs and pancreatic cancer cells, can reverse the negative effect of the tumor microenvironment on mesothelin-CAR-T cells in pancreatic cancer in vitro." (PMID 29769134, 2018). "Similar results have been reported with pancreatic carcinoma cells adhesion to hMEC-1 stimulated with IL-6; however, as far as we are aware no published data is available investigating the effect of IL-10 on tumour cell adhesion." (PMID 29256156, 2018). "Finally a recent study has shown higher levels of IL-6, IL-8, IL-10, and TNF-α and lower levels of IL-23 in pancreatic cancer patients compared to healthy controls." (PMID 28050120, 2016). "Finally, immunohistochemical analysis shows that IL-10 is expressed in 68.3% of pancreatic cancer patients, whereas 31.7% present negative expression for this cytokine." (PMID 38785507, 2024). "RNA-sequencing (RNA-seq) of pancreatic tumor lysates and principal component analysis revealed that KC;iASPPΔ8/Δ8 pancreata bear closer resemblance to KC than KPC pancreata and express greater Cd3, Cd4, Itgae, Pdcd1, Il10, Ccl5, Osm, and Cd274, reflective of an immunosuppressive stromal reaction." (PMID 36746936, 2023). "However, the relationship between IL-10 and HO-1 in pancreatic cancer has not been clearly identified." (PMID 34066839, 2021). "In relapsed pancreatic cancer, a phase III clinical trial showed no statistical difference between FOLFOX (folinic acid + fluorouracil + oxaliplatin) in association with pegylated IL-10 compared to FOLFOX alone." (PMID 34832887, 2021).
pancreatic cancer (continued). "These cytokines, such as interleukin-1β (IL-1β), IL-6, IL-8, IL-10, tumor necrosis factor-α (TNF-α), and transforming growth factor-β (TGF-β) are potential prognostic biomarkers as well as targets in the pathogenesis of pancreatic cancer and in peripheral nerve injury." (PMID 32174830, 2020). "IL-6 and IL-10 were significantly increased in both the HCC and GBC groups, whereas IL-2, IL-6, IL-10, and TNF-α were significantly increased in the cholangiocellular carcinoma group, and IL-2, IL-6, IL-8, and TNF-α were significantly increased in the pancreatic cancer group." (PMID 29410961, 2017).